PAK1 (p21 (RAC1) activated kinase 1)
Diseases named in the same sentence as PAK1 in open-access papers (continued):
Sharing a sentence is not in itself a finding about the gene and the disease.
breast carcinoma (continued). "Silencing PAK1 in F. nucleatum‐colonized breast cancer cells significantly reduced their proliferative and migratory capabilities." (PMID 40070022, 2025). "In contrast, NCK1 can interfere with the prolactin-activated JAK2/PAK1 axis, which plays a role in breast cancer promotion." (PMID 40001545, 2025). "More recently, Pak1 was shown to directly phosphorylate and activate CaMKII in breast cancer, and dual inhibition of Pak1 and CaMKII synergistically reduced proliferation, migration, invasion, and xenograft growth in triple-negative and Her2+ models." (PMID 41283247, 2025). "Studies have indicated that amplification of the PAK1 gene occurs in around 30% of breast cancer cases." (PMID 40070022, 2025). "We demonstrate here that pTyr-PAK1 regulates epithelial-mesenchymal transition (EMT) in breast cancer cells." (PMID 38660565, 2024). "Altogether, our current data provide insight into the mechanism of PRL- and PAK1-stimulated EMT of breast cancer cells." (PMID 38660565, 2024). "pTyr- PAK1 also stimulated invasion of breast cancer cells in response to PRL and three-dimensional collagen IV(Rider, Oladimeji, & Diakonova, 2013)." (PMID 38660565, 2024). "PAK1 is a well-established regulator of macropinocytosis, and it has been shown to be up-regulated in a variety of cancer types, including breast cancer." (PMID 38227562, 2024). "Both PAK1 activities are important for PRL-dependent breast cancer cell adhesion, motility, and invasion." (PMID 38660565, 2024). "Previously, we have shown that pTyr-PAK1 plays a significant role in PRL-induced breast cancer cell motility and metastasis in micein vivoas only cells overexpressing PAK1, but not PAK1 Y3F, were able to migrate from the primary tumor to the lungs." (PMID 38660565, 2024). "Targeting PAK1 emerges as a promising therapeutic strategy for this aggressive subtype of breast cancer." (PMID 39473450, 2024). "The importance of PAK1 phosphorylation at a tyrosine residue has been reported to mediate the synergistic activation of breast cancer cells by ERα and estrogen." (PMID 37190165, 2023). "Follow-up findings established that PAK1 hyperactivation and inactivation are sufficient to convert noninvasive breast cancer cells to invasive cells and vice-versa, respectively." (PMID 36830998, 2023). "Equally important in the resistance of RAMA 37-28 cells to tamoxifen alone is PAK1, whose overexpression and the role in tamoxifen resistance of breast cancer patients has already been described." (PMID 37239828, 2023). "Overexpression of the constitutively active form (T423E mutant) of PAK1 in breast cancer cell lines stimulated anchorage-independent growth in vitro, resulting in mammary epithelial hyperplasia and, breast carcinomas in mice." (PMID 37190165, 2023). "Pharmacological inhibition of PAK1 suppresses breast cancer motility and invasion and potentiates the effects of microtubule-stabilizing agents, restoring tamoxifen sensitivity in breast cancer cells." (PMID 37190165, 2023). "MMP1-3 secretion in breast cancer cells is stimulated by the activation of the PRL/PAK1 signaling pathway via COL4A1." (PMID 38004422, 2023). "At the same time, PAK1 was shown to be co-amplified with three other genes at chromosome 11q13.5 to 11q14.1 in breast cancer cells." (PMID 36830998, 2023). "Remarkably, increased pericellular proteolysis observed in a model of pre-malignant progression of breast cancer was reliant on increased PAK1 activity." (PMID 37190165, 2023). "PAK1 ameliorates tamoxifen resistance in breast cancer by phosphorylating other target substrates like Aurora A kinase, C-Terminal Binding Protein (CtBP), and ErbB3-binding protein 1 (EBP1)." (PMID 36830998, 2023). "Cyclin D1 (CCND1) has been found to be overexpressed in breast cancer, and PAK1 is shown to regulate the expression of CCND1 in BC." (PMID 37368917, 2023). "A role for Rac1/PAK1/miRNA142 signaling in tumorigenesis has further been reported in breast cancer cells." (PMID 37190165, 2023).
breast carcinoma (continued). "In the Cox regression analyses using mean PAK1 CN <4 as the reference, no significantdifference was observed in the rate of death from breast cancer for cases with PAK1 CN increase (HR 1.4 [95% CI 0.8–2.7]) for cases with mean PAK1 copy number ≥6)." (PMID 37368917, 2023). "PAK1 phosphorylates ER in breast cancer cells, thereby inducing a resistance to antiestrogen therapy." (PMID 36230657, 2022). "PAK1/4 regulates the occurrence and development of breast cancer through downstream target proteins in breast cancer cells or tissues." (PMID 36230657, 2022). "In breast cancer, ivermectin decreases p21-activated kinase 1 (PAK1) expression by promoting its degradation and inducing cell autophagy." (PMID 36050295, 2022). "PAK1/4 regulates the invasion and metastasis of breast cancer cells, either by promoting the secretion of MMP-1/3, or through the LIMK1/Cofilin signaling pathway or via Snail-induced EMT." (PMID 36230657, 2022). "Increased PAK1 expression and activity in breast cancer is correlated with higher tumor grade and higher invasiveness." (PMID 36077661, 2022). "Recent evidence suggests that Pak1 plays an important role in the development and progression of human breast cancer." (PMID 35111748, 2021). "As Pak1 and CaMKII are co-expressed and interact in human breast cancer cells, we tested the effect of small-molecule inhibitors of these kinases, alone and in combination, on the survival of Luminal, Her2 positive and TNBC cells." (PMID 35111748, 2021). "To investigate the protein expression patterns of Pak1 and CaMKII in human breast cancer, we used a TMA containing normal and tumor samples for IHC staining." (PMID 35111748, 2021). "Ivermectin, a broad-spectrum antiparasitic drug, inhibited breast cancer cell growth by activating cytostatic autophagy by promoting ubiquitination degradation of PAK1." (PMID 35096055, 2021). "p21-Activated kinase-1 (Pak1) is frequently overexpressed and/or amplified in human breast cancer and is necessary for transformation of mammary epithelial cells." (PMID 35111748, 2021). "Except for playing a role via Raf/MEK/ERK pathway, PAK1 can also phosphorylate ER and promote its transcription, thus up‐regulating the expression of cyclin D1 and promoting hormone‐dependent breast cancer cell growth." (PMID 34651424, 2021). "In Luminal A breast cancer, higher expression of MARK2, NUAK2, and PAK1 was significantly associated with improved survival in both pre- and post-chemotherapy groups." (PMID 34084284, 2021). "Previous studies showed that PAK1 was innately associated with ERK pathway in various tumors, such as melanoma, breast cancer, malignant peripheral nerve sheath tumors and Non-small cell lung cancer." (PMID 34307365, 2021). "While these studies focused on prostate cancer, we have also previously shown that the ability of SSL-IPA-3 to decrease cell growth was dependent on the expression of PAK-1 in a diverse set of breast cancer cells." (PMID 33321758, 2020). "Studies using RNA interference targeting PAK-1 in breast cancer cells revealed major roles of PAK-1 in cell survival and transformation." (PMID 33321758, 2020). "For example, it has been demonstrated that PAK1 is increased in breast cancer and plays a pivotal role in promoting tumor growth and drug resistance." (PMID 32411180, 2020). "PAK1, an oncogene in breast cancer, was identified as a target of miR-494 and thereby inhibiting breast cancer proliferation, colony-formation and cell motility." (PMID 32132611, 2020). "p21 (RAC1) activated kinase 1 (PAK1) can also phosphorylate β-catenin at Ser675 in colon cancer cells and can be activated by oestrogen in breast cancer cells, while its transcription is also oestrogen responsive." (PMID 33171657, 2020). "Breast cancer is heterogeneous and is characterized by altered expression and/or activity of different protein kinases such as the p21-activated kinase-1 (PAK-1)." (PMID 33321758, 2020).
breast carcinoma (continued). "PAK1 gene amplification or protein overexpression was observed in many kinds of tumors, including ovarian cancer, breast cancer, colorectal cancer, and hepatocellular carcinoma 9-11." (PMID 32863957, 2020). "In Tamoxifen-resistant breast cancer cells, the inhibition of PAK1 restores the sensitivity of cancer cells to tamoxifen to improve the therapeutic effect." (PMID 32863957, 2020). "There is a strong correlation between increased nuclear localization of PAK-1 and resistance to the anti-estrogen tamoxifen in breast cancer." (PMID 33321758, 2020). "For one case, PAK1 phosphorylates histone H3 to regulate chromosome dynamic for further cell cycle regulation in breast cancer cells." (PMID 32863957, 2020). "Together, these results provided a novel chemical scaffold as PAK1 inhibitor for breast cancer treatment." (PMID 32752894, 2020). "To investigate the role of PAK1 in invadopodia formation and disassembly we generated shRNA knockdowns of PAK1 in the breast cancer cell line MDA-MB-231 (shPAK1)." (PMID 30651600, 2019). "Our results indicate that combined inhibition of AURKA and PAK1 is of potential value for the treatment of breast cancer, with greatest efficacy seen in luminal HR + and HER2 + subtypes in vitro." (PMID 31254157, 2019). "We discussed the correlation of PAK1/IL-6 and Stat3/IL-6 in breast cancer patient from the publicly available dataset such as TCGA (The cancer genome atlas)." (PMID 31658701, 2019). "PAK‐1 expression was identified in four different breast cancer cell lines, and in a melanoma cell line." (PMID 31516713, 2019). "This current study also investigated the ability of PAK‐1 gene silencing to alter prostate and breast cancer cell growth and alter markers of EMT." (PMID 31516713, 2019). "PAK‐1 inhibition using shRNA correlated with decreased cell migration and invasion in prostate cancer DU‐145 and breast cancer MCF‐7 cells." (PMID 31516713, 2019). "Increased PAK1 activity is also common in breast cancer, typically due to amplification of the PAK1 gene (30% of breast carcinomas)." (PMID 31254157, 2019). "Our observations suggest that PAK1 and Stat3 interact and colocalize in the nucleus in breast cancer cell lines." (PMID 31658701, 2019). "Our observations suggest that the reduction in nuclear PAK1 is important for mammosphere formation in breast cancer lines." (PMID 31658701, 2019). "PAK1 has been shown to play a role in invadopodia disassembly in breast carcinoma cell lines and it has also been suggested to regulate invadopodia formation in melanoma cells." (PMID 30651600, 2019). "Together, our results provide evidence that dual inhibition of AURKA and PAK1 is of value in breast cancer." (PMID 31254157, 2019). "We chose to study the effect of PAK‐1 molecular inhibition on prostate and breast cancer cell growth using DU‐145 and MCF‐7 cells." (PMID 31516713, 2019). "AURKA promotes epithelial-mesenchymal transition and stem cell properties of ER + breast tumors in a mechanism involving overexpression of HER2, while PAK1 is an essential mediator of HER2 signaling in mammary tumors dependent on this protein." (PMID 31254157, 2019). "For example, PAK1 amplification drives the anchorage-independent growth of breast cancer cell lines, while duplications of PAK1 and 4 correlate with poor outcomes in patients with ovarian cancer." (PMID 29875996, 2018). "In a murine MCF‐7 breast cancer model, PAK1 promoted proliferation and anchorage‐independent growth." (PMID 28707321, 2017). "MiR-494 suppresses breast cancer proliferation, colony forming, migration and invasion though PAK1 dysfunction." (PMID 28055013, 2017). "Filamin A is an actin cross-linking protein that can be phosphorylated by PAK1 at Ser2152 and is involved in PAK1-dependent membrane ruffling in mammalian breast cancer cells." (PMID 29209279, 2017). "Remarkably, the expression of PAK1 is inversely correlated with the level of miR-494 in human breast cancer samples." (PMID 28055013, 2017).
breast carcinoma (continued). "The PAK1 gene product has many roles in cancer, including breast cancer progression, development and maintenance of a metastatic phenotype of breast cancer cells, and a predictor of recurrence and tamoxifen resistance in postmenopausal breast cancer." (PMID 28391240, 2017). "PAK1, which acts as an oncogene in breast cancer by activating MAPK signal pathway and remolding cytoskeletal, is demonstrated to be a functional target gene of miR-494." (PMID 28055013, 2017). "More importantly, staining of PAK1 and miR-494 in breast cancer samples shows that expression of PAK1 is inversely correlated with that of miR-494." (PMID 28055013, 2017). "Pak1 signaling promotes trans-activation of ERα in breast cancer cells by phosphorylating ERα at serine 305 in the absence of its ligand estrogen, resulting in tamoxifen resistance." (PMID 28978098, 2017). "Collectively, these data supported that miR-494 directly targeted PAK1 in human breast cancer cells and specimens." (PMID 28055013, 2017). "Our lab has previously demonstrated that PRL-activated tyrosine kinase JAK2 phosphorylates PAK1 on tyrosines 153, 201, and 285, and that tyrosyl phosphorylated PAK1 (pTyr-PAK1) augments migration and invasion of breast cancer cells." (PMID 27542844, 2016). "Combined inhibition of PAK1 and PARP in PAK1 overexpressing breast cancer cells had a synergistic effect, enhancing apoptosis, suppressing colony formation, and delaying tumor growth in a xenograft setting." (PMID 27740936, 2016). "The PARP inhibitor alone had a nearly identical effect in the survival of all breast cancer cell lines, and as expected, PAK1 overexpressing and PAK1-amplified breast cancer cells were much more sensitive to PAK inhibition than HCC1419 cells." (PMID 27740936, 2016). "Aberrant expression/activation of PAK1 has been described in breast cancer as well as among several other cancers including brain, pancreas, colon, bladder, ovarian, hepatocellular, urinary tract, renal cell carcinoma, and thyroid cancers." (PMID 27542844, 2016). "The PAK1 gene lies within the 11q13 region and 11q13.5 → 11q14 amplifications involving the PAK1 locus are present in 17 % of breast cancers." (PMID 27542844, 2016). "Next, the expression level of two FA/BRCA genes, FANCD2 and FANCI, was confirmed by qPCR and western blot in PAK1 depleted human breast cancer cells." (PMID 27740936, 2016). "We use T47D and TMX2-28 breast cancer cells stably overexpressing GFP, PAK1 WT, or tyrosyl phosphorylation-deficient mutant of PAK1 in which the three JAK2 phosphorylation sites have been mutated to phenylalanine (PAK1 Y3F)." (PMID 27542844, 2016). "Here we further investigate the mechanisms by which pTyr-PAK1 enhances breast cancer cell motility in response to PRL." (PMID 27542844, 2016). "Remarkably, we found that PAK inhibition sensitizes PAK1 overexpressing breast cancer cells to PARP inhibition." (PMID 27740936, 2016). "Here we extend our knowledge on the role for pTyr-PAK1 in PRL-induced breast cancer cell motility and invasion." (PMID 27542844, 2016). "Treatment of PAK1 overexpressing and PAK1-amplified breast cancer cells with each of these drugs had a similar effect, and interestingly, coadministration of both inhibitors caused a very significant reduction (72-78 %) in cell survival." (PMID 27740936, 2016). "HCC1419, BT-474, MDA-MB-361 and SK-BR-3 breast cancer cells were treated with vehicle or PF-3758309, or transfected with PAK1 targeting siRNAs and exposed to cisplatin." (PMID 27740936, 2016). "We have previously demonstrated that PRL promotes breast cancer cell motility in a pTyr-PAK1-dependent manner." (PMID 27542844, 2016). "PAK1 has been previously found to promote the cell invasion of colon cancer and breast cancer cell lines." (PMID 27765920, 2016). "In order to test the cellular activity of FRAX1036, breast cancer cell lines with known PAK1 gene amplification status were tested for levels of PAK1 expression and activity." (PMID 25902869, 2015).
breast carcinoma (continued). "Taken together, these findings further support PAK1 as a potential target in breast cancer and suggest combination with taxanes as a viable strategy to increase anti-tumor efficacy." (PMID 25902869, 2015). "PAK1 dysregulation (copy number gain, mRNA and protein expression) was evaluated in two cohorts of breast cancer tissues (n = 980 and 1,108)." (PMID 25902869, 2015). "We also introduce a novel ATP-competitive small molecule inhibitor of group I PAKs, FRAX1036, and demonstrate sensitivity of PAK1-amplified breast cancer cells to this compound." (PMID 25902869, 2015). "We and others have documented proliferative role of Pak1 in other human cancers, such as breast cancer, squamous nonsmall cell lung carcinoma and choriocarcinoma." (PMID 26218748, 2015). "Consistent with previous reports, PAK1 mRNA expression was correlated with copy number gain and elevated in luminal breast cancer subtypes in METABRIC samples." (PMID 25902869, 2015). "In breast cancer cells, Pak1 inhibitor blocked ER transactivation functions and downregulated ER target product PR (both PRA and PRB isoforms) protein expression." (PMID 26218748, 2015). "A bioinformatics analysis showed elevated Pak1 expression in several solid tumors relative to adjacent normal tissue, with both Pak1 and E2F increased relative to normal tissue in breast cancer, supporting a cancer etiology for Pak1 up-regulation." (PMID 26555075, 2015). "The miRNA let-7b-5p was also shown to have a tumor suppressor role in breast cancer patients with lymph node metastasis, by repressing the expressions of the genes PAK1, DIAPH2, RDX and ITGB8." (PMID 26763900, 2015). "For instance, PAK1−/− mouse embryonic fibroblasts display decreased microtubule regrowth and polymerization compared with wild-type cells, and the reciprocal phenotypic was observed using MCF7 breast cancer cells overexpressing PAK1." (PMID 25902869, 2015). "Taken together, these results suggest that further investigation of PAK1 as a therapeutic target in breast cancer is warranted." (PMID 25902869, 2015). "Treatment of PAK1-amplified breast cancer cells with a novel small molecule inhibitor of group I PAKs, FRAX1036, resulted in apoptosis." (PMID 25902869, 2015). "Taken together, these results indicate that PAK1 genomic amplification and overexpression are correlated with poor patient outcome in luminal breast cancer." (PMID 25902869, 2015). "PAK1-dependent phosphorylation of stathmin was observed in breast cancer cells following selective knockdown or FRAX1036 treatment." (PMID 25902869, 2015). "Analysis of breast cancer cell lines with PAK1 genomic copy number gain using RNA interference approaches revealed dependence on PAK1 expression for cell survival and transformation." (PMID 25902869, 2015). "Consistent with previous reports evaluating PAK1 function in breast cancer cell lines via genetic approaches, dose-dependent inhibition of PAK1 effector signaling was correlated with poly(ADP-ribose) polymerase (PARP) cleavage." (PMID 25902869, 2015). "Although Pak1 upregulation in solid tumors was found in all four databases we studied, E2F was slightly upregulated only in the breast cancer database." (PMID 26555075, 2015). "Successively, the expression level of its target molecule PAK1 is increased significantly, the growth and invasiveness of breast cancer cells is enhanced." (PMID 26516313, 2015). "Previous study also found that Pak1 regulates prolactin mediated cyclin D1 promoter activity in breast cancer." (PMID 26218748, 2015). "Taken together, these findings provided compelling evidences that PAK1 is critical in breast cancer progression and metastasis." (PMID 25093037, 2014). "The involvement of PAK1 in angiogenesis was revealed by the induction of vascular endothelial growth factor (VEGF) by dominant-active mutant of PAK1 in breast cancer cell." (PMID 25093037, 2014).